METTL3 (methyltransferase 3, N6-adenosine-methyltransferase complex catalytic subunit)
Diseases named in the same sentence as METTL3 in open-access papers (continued):
Sharing a sentence is not in itself a finding about the gene and the disease.
bladder cancer (continued). "Knockdown of METTL3 significantly reduced bladder cancer cell invasion, proliferation, and survival in vitro and tumorigenicity in vivo." (PMID 31921660, 2019). "As a main component in the so-called m6A ‘writer’, METTL3 was reported to have the ability to promote bladder cancer progression via AFF4/NF-κB/MYC signaling network by an m6A dependent manner." (PMID 31228940, 2019). "Data from the bladder cancer T24 cells also supported the essential role of the METTL3-m6A-CDCP1 axis in regulation of proliferation, migration, and invasion of bladder cancers." (PMID 30796352, 2019). "Overall, our in vitro and in vivo loss-of-function studies confirmed that the METTL3-m6A-CDCP1 axis is essential for the growth and progression of bladder cancer." (PMID 30796352, 2019). "The result showed that PTEN expression was negatively correlated with METTL3 expression in bladder cancer (r = − 0.35, P = 0.0088)." (PMID 31228940, 2019). "METTL3 can inhibit the sensitivity of bladder cancer cells to Metilide treatment." (PMID 41194259, 2025). "Furthermore, our previous research also revealed that METTL3 positively regulates the pri-miR221/222 process via an m6A-dependent mechanism to promote the development of bladder cancer." (PMID 40083693, 2025). "METTL3 has been reported to exert its oncogenic role in bladder cancer by regulating the maturation of miR-146a-5p in an m6A-dependent manner, wherein METTL3 knockdown led to an accumulation of pri-miR-146a and thereby reduced the expression of mature miR-146a-5p." (PMID 40338154, 2025). "Similarly, the JNK/METTL3 axis influences PD-L1-mediated T-cell activation, exhaustion, and infiltration in bladder cancer." (PMID 40279954, 2025). "The METTL3–YTHDF2–m6A signaling axis orchestrates the turnover of transcripts encoding the kruppel Like factor 4 (KLF4) and SET domain containing 7 (SETD7), thereby fueling the malignant proliferation of bladder cancer cells." (PMID 40986143, 2025). "Notably, current research underscores the therapeutic potential of targeting METTL3 to combat angiogenesis in bladder cancer." (PMID 38408075, 2024). "METTL3 contributes to the immune escape of bladder cancer cells through PD‐L1 overexpression." (PMID 39661414, 2024). "By binding to the processor protein DGCR8 and favorably controlling the pri-miR222/6 pathway in a m221A-dependent manner, METTL3 (methyltransferase-like 3) may play an oncogenic function in bladder cancer." (PMID 38329551, 2024). "METTL3‐mediated m6A modification causes MYC upregulation and is responsible for the AraC resistance of the AML cells. m6A plays a role in cisplatin resistance in gastric and bladder cancer cells due to alteration in the apoptotic process." (PMID 39661414, 2024). "Ablation of METTL3 in bladder cancer stem cells suppresses TEK and VEGFA expression." (PMID 39691597, 2024). "Similarly, in bladder cancer, METTL3 exerts oncogenic effects by interacting with DGCR8 and positively regulating the pri-miR221/222 process in an m6a-dependent manner." (PMID 39289775, 2024). "Furthermore, METTL3 inhibits the efficacy of anti-PD-L1 treatment in breast and bladder cancer, as well as the efficacy of anti-CTLA4 treatment in CRC." (PMID 38322265, 2024). "Overexpression of METTL3 significantly promoted the growth and invasion of bladder cancer cells." (PMID 39006762, 2024). "Whereas inhibition of METTL3 expression in bladder cancer (BC) by cisplatin decreases m6A modification on granulocyte colony-stimulating factors (G-CSF) mRNA and the production of G-CSF, resulting in a reduced the number of fibrocytic MDSCs (f-MDSCs) during intra-arterial infusion chemotherapy." (PMID 38322265, 2024). "METTL3 may affect the prognosis of BC by regulating the level of immune infiltration, suggesting that METTL3 is an immune-related biomarker for bladder cancer and may become an indicator for early diagnosis in the future." (PMID 39559360, 2024).
bladder cancer (continued). "Knockdown of METTL3 in bladder cancer cells rendered it less proliferative, invasive, and viable." (PMID 37284313, 2023). "The overexpression of METTL3 promoted bladder cancer cell growth and invasion." (PMID 36835633, 2023). "Recently, studies have confirmed that therapeutically targeting METTL3 may offer an alternative to anti-vascular therapy for bladder cancer." (PMID 38053093, 2023). "In bladder cancer, knockdown of METTL3 significantly inhibited cell migration and invasion." (PMID 37996892, 2023). "The results showed that the reduced expression of METTL3/YTHDF1 could lead to decreased bladder cancer cell proliferation and cisplatin sensitivity." (PMID 37108067, 2023). "Additionally, we verified that m6A can regulate GAS6 expression through METTL3 in bladder cancer cells using immunoprecipitation experiments and in vitro experiments." (PMID 37313656, 2023). "In bladder cancer, knockdown of METTL3 significantly inhibits proliferation in vivo and in vitro." (PMID 37996892, 2023). "METTL3-mediated methylation may be involved in transcriptional regulation, protein, phosphorylation and angiogenesis in bladder cancer." (PMID 38053093, 2023). "To summarize, we believe that targeting METTL3 or another m6A methyltransferase may be an effective therapeutic strategy for bladder cancer." (PMID 39872957, 2023). "In conclusion, these findings suggested that METTL3 could regulate GAS6 expression in an m6A‐dependent manner in bladder cancer cells." (PMID 37313656, 2023). "Reduced expression of METTL3 has been observed in renal cell carcinoma, bladder cancer, and CRC." (PMID 38012755, 2023). "METTL3 was upregulated in bladder cancer and correlated with poor prognosis of bladder cancer patients, thus METTL3 may serve as an oncogene in this case." (PMID 39872957, 2023). "Meanwhile, overexpression of the downstream target gene, RPN2, could rescue the effect of reduced METTL3/YTHDF1 expression on bladder cancer cells." (PMID 37108067, 2023). "Similarly, another study showed that METTL3 was significantly elevated in bladder cancer, and METTL3 knockdown dramatically suppressed cancer cell proliferation, cell invasion, and tumour formation through the AFF4/MYC/NF-kB axis cell signalling pathway." (PMID 36407103, 2022). "In a chemically induced bladder cancer model of normal human uroepithelial SV-HUC-1 cells and prostate epithelial RWPE-1 cells, METTL3 can upregulate CUB domain-containing protein 1 (CDCP1) in bladder cancer tissues using both methylation-dependent and methylation-independent mechanisms of METTL3." (PMID 36008936, 2022). "As such, the METTL3/AFF4/MYC axis contributes to bladder cancer tumorigenesis." (PMID 34185971, 2022). "Similarly, in bladder cancer, METTL3 deposited m6A on the 3′-UTR of Cdcp1, which has been found to promote migration across several cancer types, resulting in YTHDF1-mediated increases in CDCP1 translation and increased cellular migration." (PMID 35350378, 2022). "In our study, we have revealed a role of Mettl3 in angiogenesis of bladder cancer." (PMID 33681207, 2021). "Interestingly, our previous study revealed that METTL3 promoted the progression of bladder cancer by enhancing IGTA6 expression via m6A modification." (PMID 34458149, 2021). "In addition, it was discovered that the expression of METTL3 was negatively correlated to the expression of PTEN in patients with bladder cancer." (PMID 33749070, 2021). "However, other studies have shown contradictory results for METTL3 in bladder cancer, NSCLC, and liver cancer." (PMID 33795529, 2021). "Furthermore, METTL3 promoted the maturation of miR-221/222 in bladder cancer cells by recruiting DGCR8." (PMID 34108450, 2021). "In addition, conditional knockout of Mettl3 in K14+ bladder cancer stem cell population leads to inhibition of bladder cancer progression." (PMID 33681207, 2021). "In addition, a high expression pattern of METTL3 is demonstrated in bladder cancer via bioinformatic analysis." (PMID 32808488, 2020).
bladder cancer (continued). "A recent study assessed the association between METTL3 and DGCR8 in a bladder cancer model." (PMID 32209098, 2020). "In bladder cancer cells, METTL3 can interact with DGCR8 and positively regulate the pri-miR-221/222 synthesis in an m6A-based pathway, which might provide new insight on bladder cancer therapy and therapy resistance." (PMID 32122355, 2020). "In bladder cancer, METTL3 is overexpressed, which correlates with poor prognosis." (PMID 32709063, 2020). "The role of METTL3 in bladder cancer has been exclusively studied in many research centres." (PMID 32808488, 2020). "Zhao et al52 found that knockdown of METTL3 significantly promoted the proliferation of bladder cancer cell line and knockin of wild‐type METTL3 could restore their normal growth rate." (PMID 32615646, 2020). "METTL3 may maintain the characteristics of bladder cancer stem cells by inducing the m6A modification of SOX2(SRY-Box Transcription Factor 2), a marker of bladder cancer stem cells both in vivo and in vitro." (PMID 32765970, 2020). "This study confirmed the carcinogenic role of METTL3 in bladder cancer." (PMID 32398132, 2020). "The expression of METTL3 in human bladder cancer was shown to be significantly upregulated." (PMID 32398132, 2020). "Besides, AFF4 binds to the promoter of MYC, suggesting the METTL3/m6A/AFF4/NF-κB/MYC axis for bladder cancer tumorigenesis." (PMID 33099572, 2020). "It implies that METTL3 may serve as a novel prognostic and/or therapeutically target in bladder cancer." (PMID 31228940, 2019). "When we transfected miR221/222 mimics in METTL3 knockdown cells, we found miR221/222 mimics could partly increase the bladder cancer cells proliferation inhibited by the knockdown of METTL3." (PMID 31228940, 2019). "Then, we tested whether METTL3 exhibited its oncogenic role by regulating the expression of miRNA221/222 in bladder cancer." (PMID 31228940, 2019). "METTL3 was found to be upregulated in bladder cancer tissues and cell lines significantly." (PMID 31228940, 2019). "So, we assessed whether METTL3 was required for the engagement of pri-miRNAs by the DGCR8 in bladder cancer." (PMID 31228940, 2019). "Furthermore, Kaplan-Meier analysis showed that bladder cancer patients with high expression of METTL3 had worse prognosis and shorter survival time, compared with those with low expression of METTL3." (PMID 31228940, 2019). "All the results implied that METTL3 could promote the maturation of pri-miR221/222 in bladder cancer by m6A dependent manner." (PMID 31228940, 2019). "In addition, the prognosis of bladder cancer patients with high expression of METTL3 was worse, suggesting that METTL3 was a predictor of the prognosis for bladder cancer patients." (PMID 31228940, 2019). "When we transfected miR221/222 mimics or inhibitors into METTL3 knockdown and overexpression bladder cancer cells, respectively, we found that miR221/222 interference could rescue the proliferation induced by METTL3 in bladder cancer cells." (PMID 31228940, 2019). "Our findings suggested that METTL3 may have an oncogenic role in bladder cancer through interacting with the microprocessor protein DGCR8 and positively modulating the pri-miR221/222 process in an m6A-dependent manner." (PMID 31228940, 2019). "Moreover, we found that METTL3 was significantly increased in bladder cancer and correlated with poor prognosis of bladder cancer patients." (PMID 31228940, 2019). "The colony formation assay also displayed that miR221/222 mimics could partly increase the bladder cancer cells colony formation efficiency inhibited by the knockdown of METTL3." (PMID 31228940, 2019). "In bladder cancer, METTL3 could promote the bladder cancer progression via AFF4/NF-κB/MYC signaling network by an m6A dependent manner." (PMID 31228940, 2019).
bladder cancer (continued). "They further found that methyltransferase-like 3 (METTL3), an main component in the so-called m6A ‘writer’, could promote bladder cancer progression via AFF4/NF-κB/MYC signaling network by an m6A dependent manner." (PMID 31228940, 2019). "Notably, METTL3 functions as An oncogenic driver in bladder cancer by engaging in a functional interaction with DiGeorge syndrome critical region gene 8 (DGCR8), thereby enhancing the biogenesis of miR-221/222 through positive regulation of pri-miR221/222 processing." (PMID 40986143, 2025). "In addition, studies in bladder cancer demonstrate that specific circRNAs can scaffold the WTAP/METTL3/METTL14 complex to remodel m6A on target mRNAs and thereby modulate chemosensitivity, highlighting the potential bidirectional interplay between circRNAs and the m6A machinery in cancer." (PMID 41323393, 2025). "It has been demonstrated that in bladder cancer, especially in patients with poor prognosis, the overall abundance of m6A in tumor tissues is significantly increased and the expression levels of m6A-related regulators METTL3 and ALKBH5 are significantly abnormal." (PMID 38267663, 2024). "Our findings may provide theoretical basis for bladder cancer treatment targeting Mettl3." (PMID 33681207, 2021). "Our findings offer convincing evidence of Mettl3 in epigenetically modifying TEK/PI3K/VEGF cascades involving in angiogenesis, suggesting that therapeutically targeting Mettl3 may provide one of the alternatives for antiangiogenesis therapy in bladder carcinoma." (PMID 33681207, 2021). "Similarly, in bladder cancer, the METTL3-mediated m6A modification on the AFF4 could promote its expression." (PMID 33099572, 2020). "Moreover, the association between high METTL3 expression and poor prognosis in bladder cancer implies that METTL3 may become a new prognostic factor and therapeutic target for bladder cancer." (PMID 32443966, 2020). "Taken together, considering the expression pattern of METTL3 in prostate cancer, bladder cancer and other cancers, and the role of METTL3 in the carcinogenesis of prostate cancer and bladder cancer, METTL3 could be a promising biomarker and prognostic indicator in prostate cancer and bladder cancer." (PMID 32808488, 2020). "Therefore, METTL3 serves as an oncogene in the carcinogenesis of bladder cancer." (PMID 32808488, 2020). "Therefore, ITGA6 is a crucial target of METTL3 function in bladder cancer." (PMID 32765970, 2020). "In addition, an existing study indicated that the methylation enzyme METTL3 could increase the MYC expression by performing m6A modification of the MYC mRNA in bladder cancer." (PMID 33048840, 2020). "Furthermore, METTL3 was increased in bladder cancer and correlated with poor patient prognosis." (PMID 31881725, 2019). "Moreover, high expression of METTL3 was related to poor prognosis in bladder cancer patients." (PMID 31228940, 2019). "Recent research has revealed that m6A modifications, including METTL3, YTHDF1, and FTO, play a pivotal role in promoting bladder cancer development and drug resistance 15-18." (PMID 40083693, 2025). "METTL3 is known to promote cell cycle progression in cancers like HNSCC and bladder cancer and it regulates cell cycle markers such as CDK2 (cyclin-dependent kinase 2) and Cyclin D1 in gastrointestinal stromal tumors." (PMID 40338154, 2025). "CNVs of METTL3, METTL14 and METTL16 were found to correlate with the molecular characteristics of bladder cancer patients." (PMID 39559360, 2024). "Specifically, matured miR221/222 mediated by METTL3 inhibits the expression of phosphatase and tensin homolog (PTEN), contributing to the development and progression of bladder cancer." (PMID 38721006, 2024). "Altogether, our data identify METTL3/ALKBH5 and SLC3A2/SLC7A5 as the potential therapeutic targets and pave the way for future development of therapy for bladder cancer related to PAHs." (PMID 38267663, 2024).
bladder cancer (continued). "Previous studies have found that the methyltransferase METTL3 and demethylase ALKBH5 are aberrantly expressed in bladder cancer cells and are involved in the development of bladder cancer." (PMID 38267663, 2024). "METTL3 enhances the AFF4 RNA’s m6A modification and expression in bladder cancer stem cells (BCSCs), which directly controls the expression of MYC and SRY-Box Transcription Factor 2 (SOX2) in BC cells to enhance tumourigenesis in BC." (PMID 37284313, 2023). "METTL3 interacts with DGCR8 to promote miR-221/222 maturation which can promote cancer cell proliferation and growth by reducing PTEN expression in bladder cancer cells." (PMID 37437245, 2023). "For example, in bladder cancer, IGF2BP1 recognizes the m6A moiety in the vicinity of the PD-L1 stop codon, enhancing mRNA stability to induce immune escape via a METTL3-mediated m6A mechanism." (PMID 37554271, 2023). "METTL3-mediated m6A decoration is essential for promoting tumour PD-L1 expression through IGF2BP1-enhanced RNA stability in bladder cancer, and the activation of JNK signalling augments METTL3 expression." (PMID 36859310, 2023). "In bladder cancer, activated c-JUN is recruited to the METTL3 promoter to enhance METTL3 transcription." (PMID 37996892, 2023). "METTL3 is one of the most well-known m6A methyltransferases and is reported to contribute to the DDP resistance of bladder cancer, oral cancer, and seminoma through its methyltransferase activity." (PMID 35467477, 2022). "METTL3 methylates the mRNA of the tumor suppressors SETD7 and KLF4, which are then degraded by YTHDF2 to promote the development of bladder cancer." (PMID 36008936, 2022). "METTL3 can induce m6A modification of MYC mRNA and consequently increases its expression in bladder cancer." (PMID 35761379, 2022). "In further studies, METTL-3 was found to accelerate the maturation of pri-miR221/222 via interplaying with DGCR8, leading to the oncogenesis of bladder cancer." (PMID 36553003, 2022). "It was found that m6A abundantly existed in ITGA6 transcripts, and methyltransferase-like 3 (METTL3) promoted YTHDF1/YTHDF3 binding to the ITGA6 mRNA 3′-UTR, thereby enhancing ITGA6 mRNA translation and changing the adhesion ability of bladder cancer cells." (PMID 36017491, 2022). "METTL3 is significantly up-regulated and mediates AFF4-NF-κB-MYC signaling pathway, thus promoting the malignant biological behaviors of bladder cancer cells." (PMID 35022030, 2022). "Inhibition of the METTL3-m6A-CDCP1 axis can slow down the growth and progression of bladder cancer cells." (PMID 36008936, 2022). "METTL3 can affect the AFF4/NF-κB/myc signaling network in an m6A-dependent manner, promoting bladder cancer progression." (PMID 34660577, 2021). "As the Writer of m[superscript 6]A regulator genes, METTL3 and ZC3H13 were elevated in bladder cancer." (PMID 34521394, 2021). "Luckily, it was found that YTHDF2 was up-regulated in bladder cancer and the up-regulated YTHDF2 advanced the progression of bladder cancer through cooperating with METTL3 and directly degrading the mRNAs of SETD7 and KLF4 in an m6A dependent manner." (PMID 33593354, 2021). "explored that m6A writer METTL3 and eraser ALKBH5 regulator cell adhesion via embellishing ITGA6 expression in bladder cancer." (PMID 34733275, 2021). "However, the in vivo function of Mettl3 in bladder cancer remains largely unknown." (PMID 33681207, 2021). "In chemical carcinogenesis, METTL3-m6A-CDCP1 axis has synergistic effect with chemical carcinogens to promote the malignant transformation of urothelial cells and occurrence of bladder cancer in vitro and in vivo." (PMID 33952279, 2021). "Xie and colleagues have determined that the METTL3/YTHDF2 m6A axis directly degraded the mRNA of the transcription factor KLF4, contributing to the progression of bladder cancer." (PMID 34774019, 2021).